COL6A3 (collagen type VI alpha 3 chain)
Diseases named in the same sentence as COL6A3 in open-access papers (continued):
Sharing a sentence is not in itself a finding about the gene and the disease.
cancer (74 papers, 2009 to 2025). A tumor composed of atypical neoplastic, often pleomorphic cells that invade other tissues. "The most marked cluster comprised of collagen genes associated with tissue remodelling (COL1A1, COL3A1 and COL6A3); these show steady increase in expression across normal, inflamed, dysplastic and cancer tissue." (PMID 38505585, 2024). "Our Gene Ontology (GO) enrichment analysis of differentially expressed genes highlighted “cell adhesion” as one of the top-ranked GO terms closely linked to cancer, with COL6A3 being among the genes significantly associated with this GO term." (PMID 38028612, 2023). "Recently, researchers have found conclusive evidences suggesting the association between COL6A3 and plurality of cancers." (PMID 32595417, 2020). "Positive COL6A3 in cancer stromal region was significantly associated with shorter survival time (Fisher's exact test, p = 0.0326)." (PMID 26338966, 2015). "COL6A3 and EXs may serve as novel diagnostic and prognostic biomarkers in cancer and contribute to clinical therapeutic applications in the future." (PMID 39125689, 2024). "Our data show for the first time that Col6a3 plays a role in modulating signalling pathways involved in contact inhibition providing an explanation for the observed association between Col6a3 and cancer." (PMID 24498316, 2014). "The expression of COL6A3 was up-regulated in cancer, and its silencing can inhibit cancer cell proliferation, angiopoiesis, migration, invasion, and apoptosis." (PMID 41531533, 2025). "Many hypoxia-upregulated genes, including COL1A1, COL5A1, COL6A3, LAMC2, and SERPINE1, are linked to enhanced migration, invasion, immune evasion, or treatment resistance in various cancers, including NSCLC." (PMID 41009714, 2025). "Knockdown of endogenous COL6A3 suppresses the proliferation of bladder and colorectal cancer cell lines in vitro." (PMID 41228242, 2025). "Several studies are currently exploring the value of COL6A3 isoforms in cancer diagnosis and prognosis prediction." (PMID 38783078, 2024). "Collagen type VI a3 chain (COL6A3) is an extracellular matrix protein which is altered in several types of cancer." (PMID 36901727, 2023). "Within collagen genes represented in this subset (9/15), we found that all the three main COL6 genes (COL6A1, COL6A2, COL6A3) displayed an increased expression in malignant tumors, with a significant and consistent overexpression in GBM." (PMID 37505240, 2023). "Although the three strands of the collagen VI isoforms (COL6A1, COL6A2 and COL6A3) were more abundant in the cancer matrix compared to the healthy matrix in the irradiated groups, these differences were not significant in our Volcano Plots." (PMID 35897841, 2022). "Endotrophin, the cleaved C5 domain fragment of COL6A3, can directly regulate the malignancy of cancer cells via TGFβ-dependent mechanisms." (PMID 33947841, 2021). "COL6A3 knockout decreases cell proliferation and invasion, increases cell apoptosis in cancer cell lines." (PMID 32503434, 2020). "Together, 183 proteins changed upon FGF19 treatment that were involved in different aspects of metabolism (e.g. Acot2, Acox1 and Acsl3) and 267 in cell survival/cancer (Col6a3." (PMID 28178326, 2017). "Recently, COL6A3 has received increasing attention, due to its abnormal expression and the occurrence of alternative splicing in numerous types of cancer." (PMID 24765172, 2014). "Gene expression analysis of cisplatin resistant cancer cells revealed extracellular matrix related genes as a primary differentiator of chemotherapy resistance and Collagen 6A3 (COL6A3) has been shown to contribute to cisplatin resistance." (PMID 23006666, 2012). "Interestingly, the analysis of pan-cancer TCGA data showed that COL6A3 as well as COL6A1 and COL6A2 are expressed most highly in the C6 immune subtype, which is TGF-β dominant." (PMID 41228242, 2025).
cancer (continued). "However, this is largely driven by high weightings of three collagen genes; COL1A1, COL3A1 and COL6A3, which steadily increase in inflamed, dysplasia and cancer samples compared to normal tissue samples, with adjusted P-values <0.003." (PMID 38505585, 2024). "Thus, changes in the expression of many of our proposed markers (including COL6A3, MFAP2 and MFAP5) can indicate the transition of normal fibroblasts to a cancer-associated state (e.g., in in vitro experiments)." (PMID 36263012, 2022). "We found a consistent positive correlation between fibroblast proportions and expression of collagen genes belonging to fibril-forming (COL1A2) and microfibrillar (COL6A1, COL6A2 and COL6A3) subfamilies across nine cancer types, the exception being KIRC and LGG." (PMID 36321857, 2022). "Its abnormal expression in various cancers suggests that COL6A3 affects cancer formation." (PMID 34094925, 2021). "Moreover, COL6A3 expression in cancer stroma was correlated to a poor outcome with a significant prognostic value." (PMID 32878319, 2020). "Taken together, our data suggest that PRRX1 may be a target in adipocytes and potentially other cell types to modulate COL6A3 expression in the context of pathological conditions including cancer." (PMID 33214660, 2020). "Interestingly, the upregulation of COL6A3 in cancer stroma predicted poor outcome of CRC patients, as revealed by the Kaplan-Meier survival analysis." (PMID 26338966, 2015). "A list of potential partner genes of COL6A3 was generated, the majority of which are involved in cancer-related processes, and a functional network of COL6A3 was constructed, which provided promising results to enable future studies to identify the precise role of COL6A3." (PMID 24765172, 2014). "Although COL6A3 has been investigated in numerous other types of cancer, its biological mechanisms and expression pattern in GC remain unclear." (PMID 24765172, 2014). "A microarray-based co-expression network analysis was conducted and identified a total of 62 genes that were co-expressed with COL6A3, with the majority of the genes being involved in cancer-related processes, such as cell differentiation, migration and adhesion." (PMID 24765172, 2014). "A recent exon array analysis study demonstrated that an alternative long isoform of COL6A3 was expressed, almost exclusively, in cancer samples, and may potentially serve as a novel cancer biomarker." (PMID 24765172, 2014). "Particularly, the α3 chain of COL6 (COL6A3) has been highlighted as a promising candidate triggering drug resistance against platinum-based therapeutics since its levels are vastly increased in the cisplatin-resistant cancer cells in vitro." (PMID 23629957, 2013). "Hence, COL6A3 was indeed involved in the process of many cancers." (PMID 31286980, 2019). "Further, COL1A1, COL1A2, COL6A1, COL6A3, and SDC1 were upregulated in late-stage compared with early-stage patients in four cancer types." (PMID 38002057, 2023). "We further conducted coexpression analysis of COL6A members in pan-cancer, and found that COL6A1, COL6A2 and COL6A3 were highly positively correlated." (PMID 36167487, 2022). "The interactive analysis tool was applied to confirm the expression level of the eight DEGs (SPP1, TTK, MELK, FOXM1, LYN, ARRB2, COL6A3, and CCL21) in cancer and normal tissues." (PMID 33829064, 2021). "These 8 genes (SPP1, TTK, MELK, FOXM1, LYN, ARRB2, COL6A3, and CCL21) were further validated in more numbers of cancer tissue samples by quantitative real-time PCR (qRT-PCR)." (PMID 33829064, 2021). "Among these proteins, the overexpression of MMP14, ITGA2, THBS2, COL1A1, COL3A1, COL11A1 and COL6A3 has been experimentally confirmed in PDAC, while that of COL12A1 and COL5A2 has been shown in other types of cancer." (PMID 34094925, 2021). "And the positively correlation between the infiltrating levels of macrophages and the expression of COL5A1, COL6A3, and COL8A1 were confirmed in diverse cancer types using CIBERSORT method." (PMID 32523603, 2020).
cancer (continued). "We next examined correlations between expression of the collagen members COL6A3, COL5A1, and COL8A1 and markers of macrophages in the seven selected cancer types in TIMER." (PMID 32523603, 2020). "Genes co-expressed with WISP1 were mainly associated with extracellular matrix organization, with collagen members COL6A3, COL5A1, and COL8A1 being key genes correlated with macrophage infiltration and M2 polarization in pan-cancer." (PMID 32523603, 2020). "We also examined correlations between expression of COL6A3, COL5A1, and COL8A1 with M1 and M2 macrophages in the seven selected types of cancer." (PMID 32523603, 2020). "Together, these results suggest that the collagen members COL6A3, COL5A1, and COL8A1 are key genes in the seven selected cancers, reflecting alterations in ECM organization." (PMID 32523603, 2020). "In this study, we showed that COL6A3, COL5A1, and COL8A1 most likely be effector molecules of WISP1 and were positively correlated with monocyte infiltration and M2 polarization in pan-cancer." (PMID 32523603, 2020). "We identified several extracellular proteins as up‐regulated in invaded compared to noninvaded nerves (some of these were also seen in PNI compared to non‐PNI cancer), including laminins LAMA2, LAMB1, COL6A3, periostin (POST), nidogen 1 (NID1), and TNC." (PMID 30690892, 2019). "Mutations in SWI/SNF and chromatin-remodeling complex (SMARCA4, COL6A3, RYR2, and SPEG) contributed to cancer and neurological disorders." (PMID 31428092, 2019). "The biological relevance of the aberrantly methylated and expressed genes was cancer process, including IRS1 that is related to transformation, and collagen-related genes such as COL4A1, COL4A2 and COL6A3." (PMID 23818951, 2013). "Compared with other Col6 family members, Col6a3 has unique carboxy-terminal sequences that undergo proteolytic cleavage, and the released fragments exert chemotactic forces on fibroblasts and macrophages within the TME to drive cancer progression." (PMID 40166934, 2025). "Similarly, fibroblast-like cancer cells (C10) and endothelial cell-like cancer cells (C11) were identified based on the specific expression of fibroblast markers (DCN, COL1A2 and COL6A3) and endothelial cell markers (PCAT19, VWF and PLVAP)." (PMID 36451812, 2022). "PRRX1 is an established regulator of EMT in cancer cells, supporting that PRRX1 may regulate COL6A3 during EMT." (PMID 33214660, 2020). "For example, the expression of COL6A3 and COL6A1 was upregulated in most cancer types compared with controls, which play an important role in regulating the tumorigenesis and metastasis of cancer." (PMID 31627190, 2019). "Also, enhanced monocyte-macrophage trafficking and M2 polarization are correlated with expression of collagen members COL6A3, COL5A1, and COL8A1, which may orchestrate the cancer-promoting effects of WISP1." (PMID 32523603, 2020). "COL6A3, COL8A1, CDH11, and CXCL12 were not expressed in either PDAC tissues or normal tissues, and BGN and THBS2 were overexpressed in both cancer and normal tissues." (PMID 33282565, 2020).
myopathy (21 papers, 2012 to 2025). A disease of the muscle in which the muscle fibers do not function properly. "COL6A1 mice, a COLVI null model, and COL6A3 deficient mice develop a mild myopathy and tendon dysfunction possibly due to altered tendon fibrillogenesis." (PMID 27375477, 2016). "This suggests that various HIBM myopathy-specific GNE mutations could induce downstream pathogenic effects by deregulating the COL6a3 and coexpressed gene signature in HIBM myopathy." (PMID 36980840, 2023). "In addition, P56-Myo128, who presented an LGMW phenotype compatible with collagen VI-related myopathy, harbored the novel homozygous mutation c.4899del, p.Glu1634ArgfsTer32 in COL6A3." (PMID 35741838, 2022). "Besides, of particular interest is COL6A3 gene, encoding for one of the three alpha chains composing type VI collagen, that in turn is associated with Bethlem and Ullrich congenital human myopathies." (PMID 35874513, 2022). "Furthermore, one of the characterising features of myopathies related to mutations in the COL6A3 gene is joint hyper laxity." (PMID 24498183, 2014). "Common to all reported studies, COL6A3 seems to be the least represented in cohorts of patients with collagen VI-related myopathies." (PMID 41154655, 2025). "No further follow-up analysis was possible for the CNV of a part of the COL6A3 gene (BD7), so this variant remains classified as variant of uncertain significance despite the likely match with Ullrich / Bethlem myopathy." (PMID 36781956, 2023). "The patient was a heterozygous carrier of missense VUS in collagen type VI alpha 3 chain (COL6A3) gene (c.1214T>C), a reported biomarker of DCM, and fukutin (FKTN) gene (c.-7C>G), associated with both DCM and myopathy." (PMID 33567613, 2021). "Thus, the patients with high COL6a3 expression in HIBM myopathy seem to have an enrichment of pathways that affects muscle cell formation, cell development, and cell death." (PMID 36980840, 2023). "Interestingly, analysis of available patient datasets for more than six muscular disorders from GEO strengthened our trend of deregulated COL6A3 and coexpressed gene axis in many other myopathies and dystrophies." (PMID 36980840, 2023). "Since both the studies confirm COL6A3 levels to be altered in HIBM patients harboring the V727M mutation, it was selected for further analysis, as it may induce essential signaling deregulation in HIBM myopathy." (PMID 36980840, 2023). "Although the gold standard for the diagnosis of collagen VI myopathy is sequencing of the COL6A1, COL6A2 and COL6A3 genes, this technique is complicated by both the large size of the three genes (107 coding exons in total) and the high frequency of polymorphisms." (PMID 22075033, 2012). "Thus, altered expression of COL6A3 and the coexpressed gene signature identified in our study is not only limited to deregulation in HIBM myopathy but may also seem to play an equally essential role in inducing other muscular disorders." (PMID 36980840, 2023).
infection (4 papers, 2015 to 2024). The state of being infected such as from the introduction of a foreign agent such as serum, vaccine, antigenic substance or organism. "Cells within cluster 0, 1, 2, 3, and to a lesser extent cells within cluster 5 up-regulated genes associated with FRCs in response to infection, including Pdpn, Pdgfra, Pdgrfb, Vim, and Col6a3, as well as secreted factors such as Vefga and Tnfsf13b (encoding for BAFF)." (PMID 37983289, 2023). "The top 5 downregulated genes in the UB of CIE mice at 1 wk post-infection included Igf1, Col6a3, Myrf, Itga7, and Serpinf1." (PMID 36490282, 2022). "It includes genes related to collagen production and organization (COL6A3, COL6A2, COL6A1, etc.), or matrix metalloproteinases (MMP) involved in extracellular matrix remodelling (MMP7, MMP23B), and previously implicated in infection response." (PMID 26331304, 2015).
neurological disorders (4 papers, 2019 to 2024). "Thirteen OB proteins were differentially regulated in at least three neurological disorders, of which four of them (NCAM2, LY6H, COL6A3 and PRDX6) presented a homogeneous OB profile across diseases." (PMID 34768771, 2021).
connective tissue disorder (2 papers, 2020 to 2025). A disease involving the connective tissue. "Notably, of the 29 children with nFTS with dysmorphic features resembling connective tissue disorders, 7 had VUSs of genes known to be related to connective tissue (BMP4, MATN3, COL2A1, COL11A1, COL1A1, COL1A2, and COL6A3)." (PMID 40524006, 2025).
muscular disorders (2 papers, 2014 to 2023). "Since such muscular disorders are majorly associated with dysfunction of muscle fibers, we expect deregulation of COL6A3 and associated gene sets may be essential in affecting muscular functioning and cell death." (PMID 36980840, 2023). "COL6A3 is a collagen protein that has been linked to different inherited muscular disorders." (PMID 24947308, 2014). "Thus, the COL6A3-specific 13 gene signature seems to be altered in multiple muscular disorders." (PMID 36980840, 2023). "Thus, investigating this novel COL6A3-specific 13 gene signature provides valuable information for understanding the molecular cause of HIBM and may also pave the way for better diagnosis and effective therapeutic strategies for many muscular disorders." (PMID 36980840, 2023).
kidney diseases (1 paper, 2023). "COL6A3 maintains high levels of expression in all kidney diseases." (PMID 38028597, 2023).
musculoskeletal disorders (1 paper, 2023). "Thus, analysis of GNE-specific V727M mutation led to the identification of the novel COL6a3-specific 13 gene signature, altered in many musculoskeletal disorders." (PMID 36980840, 2023). "Interestingly, a highly correlated expression pattern of COL6a3 and the co-associated gene signature was observed, which was also found to be differentially expressed in musculoskeletal disorder-specific profiles." (PMID 36980840, 2023).
neurodegenerative disease (1 paper, 2023). A disorder of the central nervous system characterized by gradual and progressive loss of neural tissue and neurologic function. "The genetic study of COL6A3 in PD or other neurodegenerative diseases was insufficient." (PMID 37304079, 2023).
COL6A3 also shares sentences with these, for which no sentence is quoted: Parkinson disease (4 papers); atherosclerosis (3); metabolic disease (3); cardiovascular disease (2); fibrosis (2); ischemic stroke (2); keratosis pilaris (2); lupus nephritis (2); metastatic tumor (2); myocarditis (2); Parkinson (2); renal cell carcinoma (2); adenocarcinoma (1); alcohol dependence (1); Alzheimer disease (1); ameloblastoma (1); Arthritis (1); astrocytomas (1); brain disorder (1); brain tumor (1); breast invasive carcinoma (1); cardioembolic stroke (1); cardiomyopathy (1); cervical squamous cell carcinoma (1); channelopathies (1); cholangiocarcinoma (1); collagenopathies (1); colon adenocarcinoma (1); colorectal adenocarcinoma (1); congenital myopathies (1).
A further 53 diseases each share a sentence with COL6A3 in 1 paper.